IRF3 (interferon regulatory factor 3)
Diseases named in the same sentence as IRF3 in open-access papers (continued):
Sharing a sentence is not in itself a finding about the gene and the disease.
viral infection (continued). "YAP prevents the phosphorylation and nuclear translocation of the transcription factor IRF3, thus inhibiting IRF3-mediated production of type I interferon and interferon-stimulated genes in response to virus infection." (PMID 32857822, 2020). "Similar to mammals, increasing evidence have shown that TBK1 in fish also participate in regulating IRF3-mediated IFN signaling pathway in response to virus infection." (PMID 33584728, 2020). "IFN-regulatory factor gene family encodes multiple transcription factors including IRF1, IRF3 and IRF7, and plays essential roles in host defense against viral infection through regulation of IFN expression." (PMID 32983049, 2020). "The transcription factors IRF-7 and IRF-3 are key master regulators of type I IFN production during viral infection or after activation by TLR ligands." (PMID 32373120, 2020). "Generally, IRF3 Ser396 is targeted for phosphorylation following virus infection, which plays an essential role in IRF3 activation." (PMID 33391252, 2020). "Viral infection triggers host innate immune responses by activating transcription factors IRF3/IRF7 and NF-κB, which coordinately induce the production of type I IFNs." (PMID 32678830, 2020). "TLR-3 mediates viral double-strand RNA recognition, and IRF-3 is essentially involved in regulating TLR-3-induced interferon-β gene transcription in response to viral infections." (PMID 32734144, 2020). "The phosphorylation and nuclear translocation of IRF3 is the hallmark of its activation, which is essential for type I and III IFN induction during viral infection." (PMID 33372174, 2020). "To conclude, a recent study has shown that IRF3 is targeted by NDP52-mediated selective autophagy following sendai virus infection in a virus load-dependent manner." (PMID 33123162, 2020). "In the nucleus, formation of the IRF3/p300 complex and p300-mediated acetylation of IRF3 after virus infection is assisted by bromodomain-containing 3 (Brd3)." (PMID 32645843, 2020). "The dimerization and the translocation of IRF3 are essential for the production of IFN-β during virus infection." (PMID 33243993, 2020). "Ebola virus VP35 protein has been reported to prevent the phosphorylation, dimerization, and nuclear translocation of IRF3 induced by virus infection, thereby inhibiting the expression of type I IFN." (PMID 33584728, 2020). "The endogenous poly-Ub isolated by this method potently activated IRF3 dimerization in the cell-free system, and their expression was induced by viral infection of HEK-293T cells." (PMID 33195227, 2020). "Our results demonstrate, for the first time, that doxorubicin is a RIPA-promoting agent, which inhibits viral infection in an IRF3-dependent manner." (PMID 32295140, 2020). "The results show that the protein expression level of p-IRF3 was reduced in ZC3HAV1 knockdown cells after the viral infection by using ImageJ software." (PMID 32922375, 2020). "Collectively, our study highlights PGAM5 as an important regulator for IFNβ production mediated via the TBK1/IRF3 signaling pathway in response to viral infection." (PMID 32433485, 2020). "Phosphorylation of the constitutively expressed transcription factor IRF3 early in the cellular response to viral infection is a key event in the initial transcriptional activation of the mouse Ifna4 and Ifnb1 genes." (PMID 31076606, 2019). "PINK1 knockdown results in decreased cytokine production and attenuated IRF3 and NF-κB activation upon viral infection." (PMID 31139191, 2019). "Recently, YAP1 was identified as a negative regulator of innate immunity by interacting with IRF3 to impair dimmer formation and nuclear translocation after viral infection." (PMID 31139191, 2019). "Like TRIM21, the E3 ligase RAUL adds K48-linked ubiquitin chains to both IRF3 and IRF7 and ultimately acts as a brake on the system in response to viral infection." (PMID 30984161, 2019).
viral infection (continued). "IRF3 is a critical transcription factor that is constitutively expressed in AECs, thus enabling to quickly respond to viral infection." (PMID 31319869, 2019). "First, IRF3 is activated by virus infection and enters into the nucleus to produce IFN-β gene transcription." (PMID 31652893, 2019). "It is rapidly induced by viral infections through interferon regulatory factor 3 and by interferon signaling, and exerts antiviral activity by enhancing signaling of the RIG-I RNA sensor." (PMID 31382472, 2019). "In our study, we found that overexpression of PGRN inhibited influenza virus-induced phosphorylation of p65 and IRF3, and KO mice showed stronger activation of p65 and IRF3 than WT mice after virus infection." (PMID 31585000, 2019). "Even though chickens can induce type I IFNs robustly in response to viral infection, avian species lack IRF3, and the precise molecular and cellular mechanisms of IFN regulation remain to be elucidated." (PMID 30356848, 2018). "Recently, Xue et.al have reported that TRIM21 is upregulated upon RNA virus (SeV, VSV) infection, interacts with MAVS and catalyzes the K27-linked polyubiquitination of MAVS, thereby promoting the activation of IRF3 and inhibiting viral infection." (PMID 30410495, 2018). "Specifically, during viral infections, IRF3 is important in the early phase of inducing the transcription of IFN-α and IFN-β, which then can activate IRF7." (PMID 29515574, 2018). "Next, we compared the kinetics of IRF3 activation mediated by compartment-specific RIG-I in response to PAfsΔNS1 virus infection." (PMID 30097581, 2018). "Virus infections induce specific IRF3 phosphorylation that leads to its dimerization with itself or with IRF7 and forms a complex containing CBP/p300 and other coactivators followed by translocation into the nucleus for the expression of IFN-β." (PMID 30671058, 2018). "In our work, we found that TGR5 promotes IFN-I production via AKT-mediated IRF3 activation during viral infection in macrophages." (PMID 30333836, 2018). "Overexpression of TBK1_tv1 and TBK1_tv2 inhibits RIG-I-, MAVS-, TBK1-, and IRF3-mediated activation of IFN promoters in response to spring viremia of carp virus infection." (PMID 29441066, 2018). "Conversely, OTUD1 overexpression decreased the levels of phosphorylated IRF3 and IRF3 homodimers during viral infection." (PMID 29734366, 2018). "So it's possible that the IRF3 signaling activated upon viral infection increases the expression of IFN-β." (PMID 30333836, 2018). "Viral infection upregulates TGR5 expression in an IFN/STAT1-dependent manner which in turn amplifies the antiviral innate immune responses via AKT-mediated IRF3 activation." (PMID 30333836, 2018). "Taken together, our data reveal a positive feedback loop regulating IRF3 signaling and suggest a potential therapeutic role for metabolite-sensing GPCRs in controlling viral diseases." (PMID 30333836, 2018). "Interferon regulatory factor 3 (IRF-3) is widely known for its prompt response against viral infection by activating the interferon system." (PMID 28566697, 2017). "In the context of viral infection, activation of signaling pathways can induce IRF3 phosphorylation and dimerization, which results in IRF3 accumulation in the nucleus." (PMID 28955326, 2017). "Instead, Gsk3β mediates oligomerization and auto-phosphorylation of TBK1, a kinase responsible for IRF3 phosphorylation after viral infection." (PMID 28754897, 2017). "IRF-3 is a transcription factor that plays important regulatory roles in the interferon (IFN) system in response to virus infection." (PMID 28566697, 2017). "After MAVS activation during viral infection, IRF3/NF-κB is stimulated to induce IFN, whereas TAK1/MAPK is also activated to modulate cell proliferation." (PMID 28394926, 2017).
viral infection (continued). "It has been shown that OASL is rapidly induced upon viral infection through interferon regulatory factor 3 (IRF3), as well as IFN signaling, and that CSFV Npro interacts with IRF3 and induces its proteasomal degradation to prevent type I IFN induction." (PMID 28331099, 2017). "Both chemokines are known to be highly induced early after viral infections, and their transcription is under coordinate control of IRF3 and NF-kB." (PMID 29084253, 2017). "To further investigate the inhibitory mechanism underlying the role of ERRα in antiviral immune signaling, we explored the effect of ERRα on the TBK1-IRF3 interaction and IRF3 dimerization triggered by viral infection." (PMID 28591144, 2017). "A20 knock down results in enhanced IRF3-dependent transcription triggered by the stimulation of TLR3 or virus infection." (PMID 28210256, 2017). "Upon virus infection, IRF-3 is activated by the phosphorylation of Ser/Thr residues in its C-terminus and is translocated to the nucleus to initiate the transcription of numerous innate immune genes, including type I IFN." (PMID 28566697, 2017). "In this study, we have uncovered a novel role for the ESCRT-II subunit EAP30 in IRF3-dependent innate immune responses to viral infections." (PMID 29084253, 2017). "As the bromodomains in Brd3 has the ability to recognize acetylated proteins, we then examined the acetylation status of IRF3 after virus infection." (PMID 28045112, 2017). "Mechanistically, viral infection stabilized ERRα expression, which in turn associated with TBK1 to impede the formation of the TBK1-IRF3 complex, IRF3 phosphorylation, IRF3 dimerization and the DNA binding affinity of IRF3." (PMID 28591144, 2017). "Upon viral infection, IRF3 and IRF7 reside in the cytosol and undergoes serine phosphorylation in its C-terminal region, allowing their homo- or heterodimerization and nuclear translocation." (PMID 28915824, 2017). "Activation of TBK1 leads to adaptor phosphorylation, IRF3 activation and expression of IRF3-dependent genes that are important for the response to viral infection; thus, their activities are tightly regulated." (PMID 28591144, 2017). "Although its functional activation by viral infection has been widely explicated, the regulatory mechanism of IRF-3 gene expression in cancer cells is poorly understood." (PMID 29100282, 2017). "It was noted that total IRF3 was decreased at 7 h.p.i., probably due to virus infection-induced degradation or phosphorylation and nuclear translocation of IRF3." (PMID 28102839, 2017). "Upon viral infection, IRF-3 is activated by the phosphorylation of serine/threonine, leading to its translocation to the nucleus and dimerization." (PMID 27662626, 2016). "A similar repressive effect of Flag-FAT10 overexpression on IRF3 activity was observed after viral infection or after stimulation with the RIG-I-specific agonist, 5′ppp-dsRNA." (PMID 26996158, 2016). "IRF-3 is predominantly located in the cytoplasm and is phosphorylated and translocated to the nucleus from the cytoplasm upon viral infection." (PMID 27662626, 2016). "After viral infection, dimerized IRF-3 can be observed in the nucleus, and this dimerized IRF-3 subsequently associates with the promoter region of IRF-E, leading to enhancements in the expression of type I IFN and cytokines." (PMID 27662626, 2016). "IRF3 plays a crucial role in the innate immune responses to viral infection, especially on activating the transcription of type I IFN, and dimerization of IRF3 is a distinguishing feature of early activation of the antiviral responses." (PMID 26952111, 2016). "IRF3 has been established as an essential factor required for the production of type I IFN after virus infection." (PMID 27411355, 2016). "IRF-3 is ubiquitously expressed, and its expression is unaltered by viral infection or IFN treatment." (PMID 27662626, 2016). "Among IRFs, IRF-3 is a key molecule for the induction of type I IFNs in response to viral infection." (PMID 27662626, 2016).
viral infection (continued). "It has been demonstrated in mice that upon ssRNA viral infection, along with IRF3, IRF7 plays a key role in the induction and modulation of type I IFN expression." (PMID 26186542, 2015). "IRF3 mutant KR77/78NG in the NLS lost the ability to translocate into nucleus after viral infection." (PMID 25763818, 2015). "Viral infection triggers a series of signaling cascades, which converge to activate the transcription factors nuclear factor-κB (NF-κB) and interferon regulatory factor 3 (IRF3), thereby inducing the transcription of type I interferons (IFNs)." (PMID 26061460, 2015). "Similar to IRF7, IRF3 is very important in regulating the host immune response to virus infection in mammals." (PMID 26186542, 2015). "We observed basal phosphorylation of Optn S177 that was enhanced in response to virus infection, with a kinetic similar to that of IRF3 (on Serine 396) that reflects its activation." (PMID 25923723, 2015). "Virus infections rapidly trigger induction of IFNα and/or IFNβ through activating nuclear factor-kappa B (NF-κB) and interferon regulatory factor 3 (IRF3) transcription factors." (PMID 25812002, 2015). "Virus infection leads to the activation of transcription factor IRF3 and subsequent production of type I inteferons, which induce the transcription of various antiviral genes called interferon stimulated genes (ISGs) to eliminate viral infection." (PMID 25763818, 2015). "Viral infection activates the transcription factors NF-κB and IRF3, which contribute to the induction of type I interferons (IFNs) and cellular antiviral responses." (PMID 26407194, 2015). "Upon virus infection, IRF3 is phosphorylated at multiple serine and threonine residues near the C-terminus." (PMID 24743339, 2014). "This has been reported in the case of Sendai virus infection, where TRIM21 acts as a positive regulator of the IRF3 pathway during viral infection." (PMID 24485101, 2014). "During viral infection, phosphorylation at IRF3 S385/S386 plays an important role in regulating phosphorylation in the 396–405 Ser/Thr cluster and strengthens the association with CBP." (PMID 24904537, 2014). "Cross-talk between the NF-κB and IRF3 signaling arms is critical for determining the cellular outcome of viral infection." (PMID 24710104, 2014). "In conclusion, our study provides TRAM as a novel modulator of TLR7 mediated IRF3 activation serving as an additional element to tailor the host immune response to viral infection that mediates their effects through TLR7." (PMID 25211222, 2014). "Infection with mutant 2 led to a response somewhat similar to that observed in ΔNS1 virus infection: strong activation of IRF3, phosphorylation of eIF2α (a marker of PKR activity), and partial induction of apoptosis." (PMID 24574395, 2014). "Among the IRF family members, IRF-3 has been well documented to play a role in expression of type I interferons in response to viral infections." (PMID 24485101, 2014). "As a result, knockdown of RNF26 promoted degradation of MITA after viral infection and prevented degradation of IRF3." (PMID 25254379, 2014). "Our previous work has shown that Npro inhibits interferon signaling by accelerating the degradation of IRF3 during virus infection or when expressed alone in porcine cell lines." (PMID 24551175, 2014). "During the time-course of viral infection, the total IRF3 remained unchanged and actin was used as the internal loading control." (PMID 24722640, 2014). "IRF3 and IRF7 have been implicated as positive regulators of IFN-I gene expression induced by virus infections, whereas IRF9 constitutes an IFN-stimulated gene factor 3 together with STAT1 and STAT2, and is responsible for the induction of the IRF7 gene." (PMID 24903089, 2014). "The A30P mutation played a significant role in the differential regulation of hundreds of genes compared to the WT or A30A′ virus infections in IRF3−/−/7−/− MEFs." (PMID 25375107, 2014).
viral infection (continued). "In contrast, differentially expressed genes were abundant when comparisons included transcriptional changes induced by A30P WNVKUN virus infections but only on the background of IRF3−/−/7−/− MEFs." (PMID 25375107, 2014). "IFNλ induction depends on the same triggers and signalling pathways that regulate type I IFN expression, with the RIG-I/MAVS/TBK1/IRF3 axis being particularly relevant in mouse embryonic fibroblasts (MEFs) upon viral infection." (PMID 24278020, 2013). "Upon virus infection the transcription factor IRF3 is phosphorylated within its C-terminal domain by TBK1/IKKi to trigger its dimerization and nuclear localization." (PMID 23308279, 2013). "As an immediate response to virus infection, induced innate immune pathways typically converge and activate transcription factors such as NF-κB and IRF3." (PMID 23671700, 2013). "Previous studies have suggested that viral nucleic acids can be recognized by TLR3, and TLR7-9 in cells after viral infection, which would then lead to the production of type I interferon and inflammatory cytokines via the IRF-3 and Nf-κB pathways." (PMID 24039959, 2013). "Viral infection induces the expression of ISGs both directly (by IRF-3 after PAMP detection and PRR signaling) and indirectly (by IFN-β production and IFNAR signaling), the latter occurring in both infected and uninfected cells." (PMID 23300459, 2013). "More importantly, we demonstrated for the first time the feedback inhibition of the RLR/MAVS/IRF3-mediated antiviral innate response by activation of WNT/CTNNB1 pathway induced upon viral infection." (PMID 23785285, 2013). "Of the IRF family, IRF7 plays an important role in anti-viral responses and can be activated in a similar manner to IRF3 during viral infection." (PMID 23555825, 2013). "Using this procedure, in contrast to natural virus infection, IRF3 phosphorylation and IFN-β expression were activated." (PMID 23650567, 2013). "Overall, the loss of IRF-5 in the setting of an IRF-3 and IRF-7 deficiency renders mice more vulnerable to viral infection and early death, approaching that seen in mice that cannot respond to type I IFN." (PMID 23300459, 2013). "It was recently reported that MAVS forms large aggregates after viral infection and these species form fiber polymers with amyloid properties, which act as functional aggregates as they are highly potent in activating IRF3." (PMID 24058549, 2013). "Phosphorylation of IRF3 in response to virus infections also provides a signal for proteasomal degradation." (PMID 24086395, 2013). "Here, we demonstrate that pharmacological inhibition of GSK3 inhibited NF-κB-mediated inflammation in response to viral infection, but more importantly that this inhibition extends to IRF3-mediated antiviral responses." (PMID 23785285, 2013). "Like WT MAVS, the QN2ED mutant formed high molecular weight aggregates after virus infection, suggesting that its inability to activate IRF3 is likely due to defective recruitment of TRAF proteins rather than a defect in polymerization." (PMID 23951545, 2013). "Following virus infection, IRF-3 has also been shown to interact with the pro-apoptotic protein Bax in the cytoplasm and to translocate to the mitochondria triggering the mitochondrial intrinsic apoptotic pathway." (PMID 24100888, 2013). "Here, we show that peak levels of transcription correspond to transient recruitment of IRF7 and IRF3 to the promoters during virus infection." (PMID 22685561, 2012). "The authors demonstrated that TLR activation through IRF5 (bacterial infection) induced high levels of IL-12 and low levels of IFN-I whereas RLR activation through IRF3 (viral infection) induced high levels of IFN-I and low levels of IL-12." (PMID 23157617, 2012). "We found that activation of interferon regulatory factor 3 (IRF3) triggered by viral infection and by foreign DNA and RNA stimulation was blocked by DEN-encoded NS2B3 through a protease-dependent mechanism." (PMID 22761576, 2012).